TALDO1 (transaldolase 1)
Description:
Catalyzes the rate-limiting step of the non-oxidative phase in the pentose phosphate pathway. Catalyzes the reversible conversion of sedoheptulose-7-phosphate and D-glyceraldehyde 3-phosphate into erythrose-4-phosphate and beta-D-fructose 6-phosphate. Not only acts as a pentose phosphate pathway enzyme, but also affects other metabolite pathways by altering its subcellular localization between the nucleus and the cytoplasm (By similarity).
Synonyms: TAL; TALDOR; TAL-H; TALH
Tractability: PROTAC: ubiquitination databases record sites on it; its protein half-life has been measured.
Target class: Enzyme; Transferase
Gene: Protein-coding gene on chromosome 11 (747,399 to 765,035, forward strand). Ensembl gene ENSG00000177156.
Subcellular location: Nucleus (Isoform 1); Cytoplasm; Cytoplasm (Isoform 2)
Subcellular location (Human Protein Atlas): Cytosol
Pathways (Reactome):
Disease: TALDO1 deficiency: failed conversion of Fru(6)P, E4P to SH7P, GA3P; TALDO1 deficiency: failed conversion of SH7P, GA3P to Fru(6)P, E4P
Metabolism: Insulin effects increased synthesis of Xylulose-5-Phosphate; Pentose phosphate pathway
Cellular responses to stimuli: NFE2L2 regulates pentose phosphate pathway genes
Immune System: Gene and protein expression by JAK-STAT signaling after Interleukin-12 stimulation
Gene Ontology:
Molecular function: protein binding; transaldolase activity; carbohydrate binding; monosaccharide binding
Biological process: pentose-phosphate shunt, non-oxidative branch; carbohydrate metabolic process; fructose 6-phosphate metabolic process; glyceraldehyde-3-phosphate metabolic process; pentose-phosphate shunt
Cellular component: cytosol; extracellular exosome; nucleus; cytoplasm
Genetic constraint (gnomAD): Loss-of-function variants: 30 observed, 40.1 expected, observed/expected ratio (o/e) 0.75, 90% interval 0.56 to 1.01. The upper end of that interval is the gene's LOEUF score, 1.01, which puts it in group 4 of 6, group 1 being the genes least tolerant of losing a copy. Missense variants: 499 observed, 448.8 expected, observed/expected ratio (o/e) 1.11, 90% interval 1.03 to 1.2. Synonymous variants: 207 observed, 181.02 expected, observed/expected ratio (o/e) 1.14, 90% interval 1.02 to 1.28.
Homologues: Orthologues: chimpanzee TALDO1 (99% identical), macaque TALDO1 (97% identical), guinea pig TALDO1 (95% identical), rat Taldo1 (95% identical), mouse Taldo1 (94% identical), dog TALDO1 (94% identical), pig TALDO1 (91% identical), tropical clawed frog taldo1 (84% identical), Drosophila melanogaster Taldo (64% identical), zebrafish taldo1 (63% identical), Caenorhabditis elegans tald-1 (58% identical).
Diseases named in the same sentence as TALDO1 in open-access papers:
TALDO1 is named in the same sentence as 63 diseases in open-access papers, as found by Europe PMC text mining. Sharing a sentence is not in itself a finding about the gene and the disease. The quoted sentences say what the papers report.
hepatocellular carcinoma (9 papers, 2014 to 2025). A malignant tumor that arises from hepatocytes. "TALDO1 deficiency has been implicated in a widening spectrum of diseases including male infertility, acetaminophen-induced acute liver failure, cirrhosis, hepatocellular carcinoma and autoimmunity diseases." (PMID 24809979, 2014). "In hepatomas, TALDO1 activity was increased by 1.5–3.4 times compared to normal liver tissue regardless of tumor stage." (PMID 33499132, 2021). "Regarding TALDO1, previous studies have highlighted its overexpression in head and neck carcinomas, gastric cancer, colorectal cancer, upper tract urothelial carcinoma, ovarian cancer, and hepatocellular carcinoma metastases." (PMID 39997396, 2025). "TALDO1 is indicative of hepatocellular carcinoma metastasis." (PMID 33499132, 2021). "Comparisons between hepatocellular carcinoma and healthy liver samples using these models indicate that tumors display an increased abundance of NADPH-producing enzymes (e.g., ME1, G6PD, TALDO1, and TKT) and that H2O2 may be used as reporter metabolite in some of the patients." (PMID 28744456, 2017).
breast carcinoma (8 papers, 2017 to 2025). "They show that SLC1A5 co-expression with Transaldolase 1 (TALDO1) metabolic enzyme in receptor-positive breast cancer cells is associated with failure in endocrine therapy with tamoxifen." (PMID 38705513, 2024). "Majority of targeted therapy in breast cancer and ovarian cancer focus on HER-2, through CRISPR/Cas9 loss of function screen, Xiao-Fan Wan manifests that TALDO1 is critical for the survival of breast cancer cell line with the treatment of HER2 inhibitor." (PMID 35372044, 2022). "Further analysis on the subgroup of patients who were treated with endocrine therapy alone revealed that TALDO1 remains a predictive marker of high risk to recurrence, distant metastasis and risk of breast cancer death (P < 0.05)." (PMID 34282517, 2021). "In luminal breast cancer, SLC1A5 + TALDO1 + co-expression was predictive of a high recurrence risk and death from breast cancer (P < 0.05)." (PMID 34282517, 2021). "Our results found that high TALDO1 mRNA expression was significantly associated with a high risk of distant metastasis and death from breast cancer (P < 0.05) in the METABRIC cohort." (PMID 34282517, 2021). "As expected, IGF1R deficiency was able to significantly increase breast cancer cell sensitivity to lapatinib in a three-day dose-response assay; however, among the newly identified genes, only TALDO1 depletion conferred similar sensitivity in this assay." (PMID 30323337, 2018). "Patients with high SLC1A5 expression experienced poorer outcomes following endocrine therapy, while the co-expression of SLC1A5 and TALDO1 was significantly associated with a higher risk of recurrence and mortality in breast cancer patients receiving endocrine therapy." (PMID 41154605, 2025). "Thus, patients whose tumors expressed high levels of TALDO1 experienced a higher risk of recurrence and death from breast cancer (P < 0.05) compared to patients with tumors in the TALDO1 low group who had a more favorable clinical outcome." (PMID 34282517, 2021). "Furthermore, our results revealed that high expression of TALDO1 mRNA and protein are significantly associated with poor outcomes in patients with luminal breast cancer." (PMID 34282517, 2021). "Knockdown of SLC1A5 increased the sensitivity of luminal breast cancer cells to tamoxifen treatment, possibly by modulating the expression of the pentose phosphate pathway enzyme TALDO1, which is crucial for cancer cell growth and proliferation." (PMID 39973065, 2025). "The same group of researchers also investigated the co-expression of ASCT2 and glycolytic enzyme TALDO1 in ER+ luminal breast cancer." (PMID 41154605, 2025). "To assess the clinical significance of TALDO1 expression in luminal breast cancer, we performed Kaplan–Meier analysis." (PMID 34282517, 2021). "Here, we found a prognostic utility of the amino acid transporter SLC1A5 and the metabolic enzyme TALDO1 in luminal breast cancer and endocrine therapy." (PMID 34282517, 2021). "For independent prognostic value of TALDO1 in luminal breast cancer, multivariate analysis showed that protein expression of TALDO1 independently predicted poor clinical outcome (P < 0.05)." (PMID 34282517, 2021). "We next investigated the correlation between the mRNA expression of SLC1A5 and TALDO1 and proliferation-related genes in patients with luminal breast cancer using METABRIC cohort." (PMID 34282517, 2021). "The results from mRNA analysis encouraged us to further explore the potential value of TALDO1 protein levels using IHC in a cohort (n = 435) of luminal breast cancer." (PMID 34282517, 2021). "Taken together, these findings suggest that TALDO1 is a poor prognostic marker in patients with luminal breast cancer." (PMID 34282517, 2021). "Taken together, the combined expression of SLC1A5 and TALDO1 has a utility value as a prognostic marker of poor clinical outcome in luminal breast cancer." (PMID 34282517, 2021).
breast carcinoma (continued). "TALDO1 has previously been reported as a prognostic marker of poor response to HER2 inhibition in breast cancer patients." (PMID 34282517, 2021). "This study demonstrated the prognostic value of both SLC1A5 and TALDO1 as biomarkers in luminal breast cancer." (PMID 34282517, 2021). "As our results demonstrated the prognostic value of SLC1A5 and TALDO1 singularly in luminal breast cancer, we also established the co-expression impact of these markers on the clinical outcome and efficacy of adjuvant endocrine treatment." (PMID 34282517, 2021). "Therefore, SLC1A5 and TALDO1 can be used to predict the prognosis of endocrine therapy in luminal breast cancer." (PMID 39973065, 2025). "On basis of the network analysis and positive correlation of TALDO1 with SLC1A5 in luminal breast cancer, we performed further analysis with a focus on the potential clinical role of TALDO1 in luminal breast cancer and prediction of benefit from endocrine treatment." (PMID 34282517, 2021). "However, no previous study has demonstrated the prognostic utility of TALDO1 in predicting the response to endocrine treatment in luminal breast cancer." (PMID 34282517, 2021). "Additionally, we suggest that SLC1A5 is a potential therapeutic target for overcoming endocrine resistance and demonstrates the prognostic value of both SLC1A5 and TALDO1 as biomarkers for predicting endocrine therapy guide in luminal breast cancer." (PMID 34282517, 2021). "Therefore, we studied the expression of TALDO1 mRNA with clinical outcome on luminal breast cancer samples using the METABRIC, KM-Plotter and bc-GenExMiner v4.3 datasets." (PMID 34282517, 2021). "Additionally, patients with luminal breast cancer could be classified either as having a good or poor response to endocrine therapy according to SLC1A5/TALDO1 co-expression." (PMID 34282517, 2021). "In conclusion, our findings suggested that the contribution of SLC1A5 expression in luminal breast cancer and failure of endocrine treatment might be through participation in the pentose phosphate pathway via regulation of TALDO1 expression essential for cancer cells growth and proliferation." (PMID 34282517, 2021). "Patients with SLC1A5 + TALDO1 + had the worst outcome and further analysis revealed a significant association between SLC1A5 + TALDO1 + expression and a high risk of recurrence and death from breast cancer in patients who had received adjuvant endocrine therapy only." (PMID 34282517, 2021). "Through proteomic profiling, we discovered a metabolic signature comprised of TALDO1, GPI, LDHA, SHMT2, and ADK proteins that were downregulated in Trop2-depleted breast cancer tumors." (PMID 34711841, 2021). "Transcript levels of five of the seven metabolic genes (TALDO1, GPI, SHMT2, LDHA, and ADK: 5-gene metabolic signature) and six oncogenes: TAGLN2, NOLC1, HSP90AB1, HDGF, MCM5, and NCL, were elevated in TNBC patients when compared to patients with ER+ breast cancer." (PMID 34711841, 2021).
lung carcinoma (7 papers, 2019 to 2025). "Further analysis on ALDH2, ALDH3a1, FBP1, PGD, TALDO1, and TPI1 as biomarkers on the evolution of IPF patients, their association with PJ infection, and their lung cancer risk could be relevant." (PMID 39997396, 2025). "TALDO1 overexpression has been observed in CRC tissue, while TALDO1 knockdown in lung cancer cells reduced NADPH levels with enhanced ROS accumulation, leading to growth inhibition and apoptosis." (PMID 38542474, 2024). "To substantiate our results by 6-AN treatment in lung cancer cells, we checked the expression of PPP-related genes such as G6PD, HPGD, TKT, and TALDO1 in these cells 48 h after 6-AN treatment." (PMID 34827081, 2021). "These analyses demonstrated that mRNA expression of G6PD, glutaminase (GLS), hydroxy-prostaglandin dehydrogenase 15-(NAD) [HPGD], TKT, TALDO1, ribulose-5-phosphate-3-epimerase (RPE), and transketolase-like-1 (TKTL1) were more abundant in lung cancer patient samples." (PMID 34827081, 2021).
transaldolase deficiency (6 papers, 2015 to 2025). Transaldolase deficiency is an inborn error of the pentose phosphate pathway that presents in the neonatal or antenatal period with hydrops fetalis, hepatosplenomegaly, hepatic dysfunction, thrombocytopenia, anemia, and renal and cardiac abnormalities. "Transaldolase deficiency is a rare autosomal recessive inborn error of carbohydrate metabolism caused by pathogenic/likely pathogenic biallelic mutations in the TALDO1 gene." (PMID 38440129, 2024). "Transaldolase deficiency (TALDOD) [OMIM:606003] is caused by AR-inherited homozygous or compound heterozygous mutations affecting the TALDO1 gene on chromosome 11p15.5." (PMID 37239976, 2023). "Transaldolase deficiency (TALDOD) is a rare autosomal recessive disorder that affects the pentose phosphate pathway, resulting from pathogenic variants in the TALDO1 gene." (PMID 41146780, 2025).
bladder cancer (3 papers, 2019 to 2023). "The differential proteomics of urinary EV proteins showed TALDO1 to be associated with bladder cancer." (PMID 33499132, 2021). "For instance, TALDO1, as a nearly ubiquitous enzyme, has been linked to the progression of bladder cancer." (PMID 31355144, 2019). "In this study, we established the GMII consisting of eight glutamine metabolism-related genes (ENPP1, GALK1, TALDO1, CYP19A1, FASN, AHCY, SLC7A9, and HSPG2), a high value of which is associated with poor prognosis in bladder cancer patients." (PMID 36911676, 2023). "The expression of five of the eight GMII genes (TALDO1, AHCY, FASN, GALK1 and SLC7A9) in bladder cancer tissues was higher than that in normal tissues, while ENPP1, CYP19A1 and HSPG2 were down-regulated in tumor tissues (p < 0.05)." (PMID 36911676, 2023).
COVID-19 (3 papers, 2021 to 2022). A disease caused by infection with severe acute respiratory syndrome coronavirus 2. "Conversely, increased amounts of annexin A5, eukaryotic initiation factor 4A-1 (ElF4A1) and transaldolase 1 (TALDO1) in platelets were correlated to nasopharyngeal COVID-19 viral load." (PMID 35453523, 2022). "In line with these facts, the TALDO1 levels of the platelets correlated with the nasopharyngeal virus load of the COVID-19 patients (rS = 0.481; p = 0.043; n = 18)." (PMID 34859078, 2021). "However, the significant changes regarding increased levels of ANXA5, EIF4A1 and TALDO1 are so far unique for the platelet proteome of COVID-19 patients." (PMID 34859078, 2021). "The correlations of the COVID-19-dependent platelet proteins EIF4A1 and TALDO1 with the viral load of the patients also suggest a direct replication of the virus in platelets." (PMID 34859078, 2021). "Depending on COVID-19 disease status and mortality, increased amounts of annexin A5 (ANXA5), eukaryotic initiation factor 4A-I (EIF4A1), and transaldolase (TALDO1) were found in the platelet proteome and also correlated with the nasopharyngeal viral load." (PMID 34859078, 2021).
liver failure (3 papers, 2020 to 2024). A liver disease characterized by the liver losing or has lost all of its function. "We also analyzed genomic DNA from 10 Hungarian children with liver failure, none of which contained variation in the promoter or the coding region, eight exons, of the TALDO1 genomic locus (data not shown)." (PMID 31769880, 2020). "The relatively high frequency of sequence variations in TALDO1 also indicate that most nucleotide changes may only have moderate effects on enzymatic activity without clinical consequences unless exposed to severe metabolic stress, as noted in four APAP‐induced liver failure patients." (PMID 31769880, 2020).
Parkinson disease (3 papers, 2021 to 2024). A progressive degenerative disorder of the central nervous system characterized by loss of dopamine producing neurons in the substantia nigra and the presence of Lewy bodies in the substantia nigra and locus coeruleus. "These pathways are important in the pentose phosphate pathway that involves transaldolase, which is encoded by the TALDO1 gene and has been linked to Parkinson’s disease." (PMID 38022638, 2023).
autoimmune disease (2 papers, 2014 to 2024). A disorder resulting from loss of function or tissue destruction of an organ or multiple organs, arising from humoral or cellular immune responses of the individual to their own tissue constituents. "Transaldolase 1 (TALDO1) is a rate-limiting enzyme of the pentose phosphate pathway, and its antibodies are not present in autoimmune diseases except multiple sclerosis." (PMID 39009667, 2024).
lung adenocarcinoma (2 papers, 2021). A carcinoma that arises from the lung and is characterized by the presence of malignant glandular epithelial cells. "NRF2-regulated PPP genes, including G6PD, PGD, TKT, and TALDO1 were first identified in lung adenocarcinoma A549 cells." (PMID 33859744, 2021). "Additionally, increased expression of the pentose phosphate pathway enzymes, including TALDO1, accounts for metabolic reprogramming and contributes to cell proliferation in lung adenocarcinoma cells." (PMID 34282517, 2021).
non-small cell lung carcinoma (2 papers, 2017 to 2021). A group of at least three distinct histological types of lung cancer, including non-small cell squamous cell carcinoma, adenocarcinoma, and large cell carcinoma. "In the non-small cell lung cancer model the following 5 DEPs were found to be involved in the GSH metabolism pathway (G6PD, PRDX2, IDH1, MGST1 and 6PGD), 4 DEPs in the PPP pathway (G6PD, TALDO1, TKT and 6PGD) and 1 DEP involved in the glycolysis pathway (ALDH3A1)." (PMID 28303926, 2017).
atherosclerosis (1 paper, 2025). A disease characterized by the build-up of fatty material and calcium deposition in the arterial wall resulting in partial or complete occlusion of the arterial lumen. "SELP might be involved in developing atherosclerosis and TALDO1 in obstructive coronary artery disease." (PMID 40921935, 2025).
cervical cancer (1 paper, 2020). A primary or metastatic malignant neoplasm involving the cervix. "HPV18 integration events were detected in seven tumors in total, with the most notable clusters of integration events that affected TALDO1 (NGC = 4) in cervical cancer samples." (PMID 32025001, 2020).
fungal infection (1 paper, 2012). "Up regulation of transaldolase 1 upon fungal infection has been also observed in cucumber and wheat, suggesting a more general role of this isoform in defense, whereas transaldolase 2 might have a more specific function in the incompatible interaction." (PMID 22328937, 2012).
glioma (1 paper, 2025). A benign or malignant brain and spinal cord tumor that arises from glial cells (astrocytes, oligodendrocytes, ependymal cells). "Interactions with TALDO1 and NDUFA4 suggest potential involvement in glycolysis, energy metabolism, and mitochondrial functions, which are frequently altered in gliomas." (PMID 41009755, 2025).
head and neck squamous cell carcinoma (1 paper, 2017). A squamous cell carcinoma that arises from any of the following anatomic sites: lip and oral cavity, nasal cavity, paranasal sinuses, pharynx, larynx, and salivary glands. "TALDO1 has been found increased in the head and neck squamous cell carcinoma (SCCHN), as well as in brain, bladder, breast, and esophageal cancers." (PMID 28553614, 2017).
ischemic stroke (1 paper, 2025). A stroke disorder caused by obstruction of blood flow to the brain, due to thrombotic (local blood clot formation) or embolic (due to a blood clot or other material traveling from another site) event. "Despite their known roles in cellular metabolism, the direct involvement of DBI, PGLS, GYG1, and TALDO1 in ischemic stroke remains scarce, warranting further investigation into their potential roles in stroke pathophysiology." (PMID 41342963, 2025).
nasopharyngeal carcinoma (1 paper, 2025). A carcinoma arising from the nasopharyngeal epithelium. "In the present study, we reported that the deacetylation and low expression of transaldolase 1 (TALDO1) mediated by HDAC6 weakened the inhibitory effect of TALDO1 on tumor proliferation and metastasis in nasopharyngeal carcinoma (NPC)." (PMID 41120289, 2025).